STAT3 (signal transducer and activator of transcription 3)
Diseases named in the same sentence as STAT3 in open-access papers (continued):
Sharing a sentence is not in itself a finding about the gene and the disease.
head and neck squamous cell carcinoma (continued). "However, the role of STAT3/miR-21 axis and CDK5 in head and neck squamous cell carcinoma remains unclear." (PMID 26690371, 2015). "Early in 2018, the author and her colleges have revealed that transcription factor STAT3 enhances lincRNA HOTAIR transcription by interacting with pEZH2-Serine21, instead of pEZH2-T487 in head and neck squamous cell carcinoma (HNSCC), thus promoting tumor progression and cisplatin resistance." (PMID 37803297, 2023). "In melanomas, renal cell carcinomas (RCC) and squamous cell carcinomas of the head and neck (SCCHN), phosphorylated STAT1, and not STAT3, is involved in IFNγ-triggered PD-L1 transcription." (PMID 35402280, 2022).
rheumatoid arthritis (165 papers, 2011 to 2026). A chronic, systemic autoimmune disorder characterized by inflammation in the synovial membranes and articular surfaces. "Patients with STAT3 mutations frequently present with neutropenia, symptomatic disease, rheumatoid arthritis and often have refractory/relapsed disease to multiple different treatments compared to patients without these mutations." (PMID 38610985, 2024). "In CD8+ T-LGLL, STAT3 mutations have been associated with autoimmune manifestations such as rheumatoid arthritis and neutropenia." (PMID 35210405, 2022). "T-LGL leukemia patients with STAT3 mutations often presented with rheumatoid arthritis providing a link between autoimmunity and somatic mutations in STAT3." (PMID 36441748, 2022). "The prevalence of autoimmune conditions, such as rheumatoid arthritis (RA) and autoimmune hemolytic anemia, was also higher in the STAT3 mutated cohort." (PMID 35359386, 2022). "The most prominent of these was the STAT3*D661Y mutation which is known to be present in large granular lymphocytic leukemia cases and associates with neutropenia and rheumatoid arthritis symptoms." (PMID 27932211, 2017). "Comparison of clinical characteristics of these patients showed that neutropenia and rheumatoid arthritis were more common among patients with a STAT3 mutation." (PMID 28427176, 2017). "STAT3 has a crucial role in the development of inflammatory responses and is closely associated with the pathogenesis of autoimmune diseases, such as inflammatory bowel disease and rheumatoid arthritis." (PMID 38566524, 2024). "Furthermore, JAK2/STAT3 activation has been reported to mediate testicular impairment and sperm aberrations in rheumatoid arthritis-associated testicular damage." (PMID 39065759, 2024). "Several studies have shown that patients with STAT3 mutated status are more likely to have rheumatoid arthritis, but the association between other autoimmune diseases (including SS) and the frequency of STAT3 mutations in patients with T-LGL leukemia has not been studied." (PMID 36362126, 2022). "LGLL patients with STAT3 mutations have more often neutropenia and rheumatoid arthritis (RA), and mutations may also confer reduced overall survival." (PMID 34075200, 2021). "Interestingly, T-LGLL patients with multiple STAT3 mutations have been reported to associate with concomitant rheumatoid arthritis (RA)." (PMID 32133291, 2020). "The data selected based on the results, which were obtained from the likelihood ratio test, revealed that SMAD3 and STAT3 may be possible diagnostic biomarkers for rheumatoid arthritis." (PMID 33362761, 2020). "We found recently that baseline signal transducer and activator of transcription 3 phosphorylation in peripheral blood CD4+ T cells of patients with early rheumatoid arthritis (RA) is associated with treatment response to synthetic disease-modifying antirheumatic drugs (DMARDs)." (PMID 28399940, 2017). "Indeed, we previously reported that patients with newly diagnosed rheumatoid arthritis have expanded CD8+ T-cell clones harbouring somatic mutations linked to cell proliferation, and also that STAT3 mutations were significantly associated with rheumatoid arthritis in T-LGLL patients." (PMID 34944832, 2021). "NTZ exhibited significant anti-arthritic activity through the inhibition of the STAT-3 and NF-κB pathways, emphasizing its potential as a therapeutic option for rheumatoid arthritis." (PMID 40191469, 2025). "Mechanistic studies have indicated that P. scandens suppresses Janus kinase 2–signal transducer and activator of transcription 3 phosphorylation, suggesting its therapeutic potential for rheumatoid arthritis via inflammatory pathway inhibition." (PMID 40852586, 2025). "A number of approaches are being developed to target the IL-6/JAK/STAT3 pathway some of which have been approved for use in inflammatory diseases such as rheumatoid arthritis." (PMID 40597443, 2025).
rheumatoid arthritis (continued). "M2 macrophages in the rheumatoid arthritis (RA) synovial microenvironment are particularly susceptible to ferroptosis, where the HMGB1/ Toll-like Receptor 4 (TLR4)/STAT3 axis plays a pivotal role in exacerbating synovial inflammation." (PMID 41326356, 2025). "Previous studies have demonstrated increased STAT3 activation in adult patients with rheumatoid arthritis, but less is known about STAT3 activation in polyJIA." (PMID 38431635, 2024). "A similar approach was used to investigate the expression of AMPK and STAT3 in a mouse model of rheumatoid arthritis." (PMID 39533324, 2024). "Based on the disease overlap between LGL leukemia rheumatoid arthritis (RA)a putative role for CD8+ T-cells in RA we hypothesized that STAT3 mutations may be detected in RA patient CD8+ T-cells correlate with clinical characteristics." (PMID 39497832, 2024). "EU-Idd exerts anti-inflammatory and osteoprotective effects by regulating the JAK2/STAT3 pathway in rheumatoid arthritis." (PMID 37123081, 2023). "TIPE2 regulates macrophage M2 polarization and the low expression of pro-inflammatory factors by activating signal transducer and activator of transcription 3 and NF-κB signaling pathways to treat rheumatoid arthritis." (PMID 36983674, 2023). "As a target of miR-218-5p, KLF9 controlled the autophagy, apoptosis, and oxidative stress by regulating the JAK2/STAT3 signaling pathway in rheumatoid arthritis synovial fibroblasts." (PMID 36846202, 2023). "NEAT1 reduces STAT3 levels, thereby blocking Th17 cell differentiation in PBMCs of rheumatoid arthritis patients." (PMID 37346034, 2023). "In contrary, the expression of XIST in cartilage tissues collected from 39 patients with rheumatoid arthritis was found to be upregulated, similarly to the level of STAT3 but in opposite to the level of let-7c-5p." (PMID 35796900, 2022). "For instance, synovial MSC-derived exosomal circRNAs have therapeutic potential on rheumatoid arthritis (RA) via targeting circEDIL3/miR-485-3p/PIAS3/STAT3/VEGF function module." (PMID 36339941, 2022). "In response to IL-6 stimulation, the JAK/STAT3 pathway is phosphorylated, forming the critical IL-6/JAK/STAT3 pathway in the human body, which is involved in the processes of rheumatoid arthritis, inflammatory bowel disease, and many human cancers." (PMID 36291659, 2022). "Another example in the border-zone of cancer and autoimmunity is the discovery of activating STAT3 mutations in CD8+ cells of patients with large granular lymphocyte (LGL) leukemia and rheumatoid arthritis." (PMID 34874980, 2021). "NEAT1 has also been found to target STAT3 and regulate the differentiation of Th17 cells in rheumatoid arthritis." (PMID 35069587, 2021). "Curcumol was shown to suppress the activation of STAT3 in fibroblast-like synoviocytes in patients with rheumatoid arthritis." (PMID 34314383, 2021). "In autoimmune diseases such as rheumatoid arthritis (RA) or IBDs, and especially in cancer, NF-κB activates signal transducer and activator of transcription 3 (STAT3), important for many oncogenic functions." (PMID 33803155, 2021). "It has been shown that oral administration of the selective ROCK2 inhibitor KD025 to healthy subjects or rheumatoid arthritis patients attenuates the ability of T cells to secrete IL-17 in response to stimulation ex vivo via a STAT3-dependent mechanism." (PMID 33613511, 2020). "Polyphenol extract from olive oil has also been shown to inhibit STAT3 in a model of rheumatoid arthritis." (PMID 33302351, 2020). "For example, DNA hypomethylation in STAT3 promoters contributed to rheumatoid arthritis by controlling the activation and differentiation of immune cells." (PMID 33029541, 2020). "Specifically, we found that KA-1002 significantly alleviated LPA-induced genes related with inflammation such as a role of macrophages, fibroblasts and endothelial cells in rheumatoid arthritis and STAT3 signal pathway." (PMID 32210054, 2020).
rheumatoid arthritis (continued). "Recently, it has been found that lactate uptake via SLC5A12 results in pyruvate kinase M2/signal transducer and activator of transcription 3 (PKM2/STAT3)-mediated production of IL-17 in CD4+ T cells in rheumatoid arthritis (RA)." (PMID 33086598, 2020). "Rebamipide exerted beneficial effects in a mouse model of rheumatoid arthritis (RA) by regulating Th17/Treg cell imbalance by modulating STAT3 and FoxP3 expression." (PMID 27350608, 2016). "Constitutive STAT3 phosphorylation in circulating leukocytes is common in recent-onset untreated rheumatoid arthritis and identifies patients characterized by the presence of systemic inflammation and good EULAR response to DMARD treatment." (PMID 26353115, 2015). "Treatment with an approved TNFα blocking antibody showed marked reduction in the levels of IL-6, IL-1β, and IL-17 and the expression level of STAT3 phosphorylation in relation to Th17 cell differentiation in patients with rheumatoid arthritis." (PMID 25436214, 2014). "In conclusion, icariin decreases Th17 cells and suppresses the production of IL-17, which contributes to the alleviated rheumatoid arthritis, through the inhibition of STAT3 activation." (PMID 25374443, 2014). "It has been shown that IL-6 could activate STAT3 through Janus-activated kinases (Jak), and rheumatoid arthritis patients treated with anti-Jak inhibitors in vitro saw an inhibition of lymphocyte autophagy." (PMID 36590587, 2022). "Furthermore, administration of an adenovirus expressing MT1 in mice decreased STAT3 phosphorylation and RORγt expression in synovial tissues, which attenuated rheumatoid arthritis symptoms." (PMID 34804020, 2021). "Tocilizumab, a humanized αIL-6R mAb, has been FDA approved for the treatment of several autoimmune diseases, including rheumatoid arthritis and systemic juvenile idiopathic arthritis, which demonstrates the feasibility and safety of inhibiting IL-6/STAT3 signaling systemically in human patients." (PMID 33411696, 2021). "However, some pathways, such as the role of macrophages, fibroblasts, and endothelial cells in rheumatoid arthritis, axonal guidance signaling, ceramide signaling, and STAT3 pathway, were enriched in JQ1-treated cells." (PMID 33893325, 2021). "Moreover, in SHP2-deficient OBs, STAT3 Y705 phosphorylation was elevated in response to IL6, an inflammatory cytokine that is often upregulated and associated with osteolysis in rheumatoid arthritis patients." (PMID 33500396, 2021). "In addition, hyperactivation of STAT3 is also involved in the development of several autoimmune diseases, including rheumatoid arthritis (RA) and inflammatory bowel disease (IBD)." (PMID 31980595, 2020). "This may result from decreased IL-6 seen in PTX+TCDD treated mice because IL-6-mediated STAT3 signaling is essential for Th17 differentiation and plays a central role in the pathogenesis of certain autoimmune diseases such as rheumatoid arthritis." (PMID 31681214, 2019). "Furthermore, icariin decreases Th17 cells and represses the production of IL-17, which contributes to the alleviated rheumatoid arthritis, through the inhibition of STAT3 activation." (PMID 25374443, 2014). "Furthermore, icariin decreases Th17 cells and suppresses the production of IL-17, which contributes to the alleviated rheumatoid arthritis, through inhibition of STAT3 activation." (PMID 25374443, 2014). "It was proposed that the compound may suppress the inflammatory process in rheumatoid arthritis via AP-1 and/or STAT3 modulation." (PMID 27379277, 2014). "Furthermore, icariin decreases Th17 cells and suppresses the production of IL-17, which contributes to the alleviated rheumatoid arthritis through the inhibition of STAT3 activation." (PMID 25374443, 2014). "Th17 cells are activated by STAT3 factors in the nucleus, and these factors are correlated with the pathologic progression of rheumatoid arthritis (RA)." (PMID 39825104, 2025).
rheumatoid arthritis (continued). "Indeed, STAT3 knockout is protective in a mouse model of arthritis; and tofacitinib treatment reduced synovial matrix metalloproteinases, chemokines, and phosphorylation of STAT3, which in turn correlated with clinical responses in rheumatoid arthritis." (PMID 37283752, 2023). "Somatic mutations activating STAT3 have been discovered especially in T-cell large granular lymphocytic (T-LGL) leukemias (40%) as well as in Felty syndrome (neutropenia, splenomegaly, rheumatoid arthritis) and less frequently in aplastic anemia and myelodysplastic syndrome." (PMID 36441748, 2022). "In addition, ATO may be a potential immune modulator for treatment of rheumatoid arthritis, that helps to balance of Treg and Th17 cells through modulating STAT3." (PMID 33658052, 2021). "ROCK2 inhibition significantly diminished STAT3 phosphorylation and binding to IL-17 and IL-21 promoters and reduced interferon regulatory factor 4 and nuclear hormone RORyt protein levels in T cells derived from healthy subjects or rheumatoid arthritis patients." (PMID 33613511, 2020). "In addition, Th17 immune response-related pathways (LXR/RXR Activation, Role of Macrophages, Fibroblasts ad Endothelial Cells in Rheumatoid Arthritis, IL-6 Signaling, STAT3 Signaling, LPS/IL-1 Mediated Inhibition of RXR Function, and PPAR Signaling) were also activated." (PMID 33520738, 2020). "Moreover, CXCL16 also mediates the activity of STAT3 in rheumatoid arthritis synovial fibroblasts." (PMID 31379980, 2019). "Interestingly, STAT3 mutation positive patients presented with rheumatoid arthritis significantly more often than mutation negative patients, suggesting a possible role of STAT3 mutations in these autoimmune symptoms." (PMID 27932211, 2017). "The aim of the present study was to examine constitutive signal transducer and activator of transcription 3 (STAT3) phosphorylation in circulating leukocytes as a candidate biomarker in rheumatoid arthritis (RA)." (PMID 26353115, 2015). "A significant proportion of T-LGLL patients harbor LGL clones with somatic STAT3 mutations and those with these mutations are more likely to present with rheumatoid arthritis (RA) compared to those without STAT3 mutations." (PMID 38238319, 2024). "Previous reports show that IL-1 and IL-6 alone and together downregulate FOXP3 while inducing IL-17 expression on Tregs in a STAT3-dependent way; this is also apparent in EAE and rheumatoid arthritis." (PMID 38386413, 2024). "There are also reports of IL-6-gp130–mediated signaling activity in rheumatoid arthritis, leading to JAK1 and STAT3 activity." (PMID 38139151, 2023). "The overexpression of survivin also affect signaling pathways, such as STAT3 and PIK3/Akt, and is involved in the severity of rheumatoid arthritis." (PMID 37869102, 2023). "Recent studies have shown that hsa-miR-218-5p regulates the proliferation, apoptosis, autophagy and oxidative stress of rheumatoid arthritis synovial fibroblasts by targeting Kruppel like factor 9 (KLF9) and activating JAK2/STAT3 signaling pathway." (PMID 37525657, 2023). "FSTL1 induced MMP3 and MMP13 gene expression in rheumatoid arthritis synoviocytes requiring MAPK, JAK/STAT3 and NF-κB pathways." (PMID 36497076, 2022). "Taken together, DF blocked the JAK/STAT signaling pathway by inhibiting STAT1 and STAT3 phosphorylation, which clarified the important role of JAK/STAT signaling pathway in anti-rheumatoid arthritis." (PMID 36386123, 2022). "IL-6, TNF-α and LPS stimulate the expression of E2F2 in rheumatoid arthritis synovial fibroblasts via NF-κΒ, ERK and STAT3 pathway." (PMID 33530456, 2021). "In rheumatoid arthritis patients, MCT1-driven lactate uptake into CD4+ T cells results in increased interleukin 17 (IL17) production via nuclear pyruvate kinase M (PKM2)/signal transducer and activator of transcription 3 (STAT3) signaling." (PMID 34177945, 2021).